SILC1 (sciatic injury induced lincRNA upregulator of SOX11)
Synonyms: FLJ30594; LOC150622; formerly LINC01105
Gene: Long non-coding RNA gene on chromosome 2 (5,932,543 to 6,060,570, forward strand). Ensembl gene ENSG00000232044.
Diseases named in the same sentence as SILC1 in open-access papers:
SILC1 is named in the same sentence as 6 diseases in open-access papers, as found by Europe PMC text mining. Sharing a sentence is not in itself a finding about the gene and the disease. The quoted sentences say what the papers report.
Ewing sarcoma (1 paper, 2023). A small round cell tumor that lacks morphologic, immunohistochemical, and electron microscopic evidence of neuroectodermal differentiation. "RNA-seq data from the Cancer Cell Line Encyclopedia74 show that the neighbouring genes, SILC1 and LOC400940, are not expressed in Ewing sarcoma." (PMID 36658220, 2023).
cancer (2 papers, 2023 to 2024). A tumor composed of atypical neoplastic, often pleomorphic cells that invade other tissues. "NcRNA genes whose polymorphic variants have been associated with cancer risk included NNT-AS1, LINC01116, and SILC1, which matched the TRIM33 gene with a score of 903 (%ID 91.8%), 577 (%ID 98.7%), and 466 (%ID 97%), respectively." (PMID 38929849, 2024).
SILC1 also shares sentences with these, for which no sentence is quoted: neuroblastoma (2 papers); infection (1); ocular toxoplasmosis (1); tumor (1).